ESR2 (estrogen receptor 2)
Diseases named in the same sentence as ESR2 in open-access papers (continued):
Sharing a sentence is not in itself a finding about the gene and the disease.
parathyroid disease (1 paper, 2025). "Although classified as VUS, several candidate genes previously reported to be associated with parathyroid disease, including ITPR2, IL21R, MMP14, TWIST1 and ESR2 were identified in three patients with cancer-type tumors." (PMID 40434298, 2025).
polyp (1 paper, 2025). A usually exophytic mass attached to the underlying tissue by a broad base or a thin stalk. "Estrogen can activate estrogen receptor beta (ERβ/ESR2) in the colon, promoting apoptosis and reducing polyp formation, thereby inhibiting the early stages of colorectal carcinogenesis through mechanisms that might overlap with those of dietary fiber." (PMID 40607022, 2025).
Thoracic scoliosis (1 paper, 2020). "On the convex side of thoracic scoliosis, the correlation between ESR2 expression and mean methylation level in promoter 0N was weak, negative, and non-significant (Spearman's rank correlation, R = − 0.3; P = 0.2)." (PMID 33339862, 2020). "In the case of the exon 0N region, the significant, negative correlation between ESR2 expression and methylation level was observed at only one CpG site on the convexity of thoracic scoliosis (R = − 0.4; P = 0.02)." (PMID 33339862, 2020).
tooth agenesis (1 paper, 2023). A tooth disease characterized by failure to develop one or more missing teeth. "Regarding polymorphisms in ESR2 (rs1256049 and rs4986938), tooth agenesis was also associated with rs4986938.43,44 Odontogenesis is under strict molecular control, thus, an alteration in different genes/molecules can lead to tooth agenesis." (PMID 37792810, 2023).
tumor (665 papers, 2002 to 2026). "The direction of association diverged by tumor type: BRCA showed adverse outcomes for ESR2-Altered cases (HR > 1), whereas UCEC and OV showed favorable outcomes (HR < 1), each with FDR-significant OS separation." (PMID 41153361, 2025). "In our analysis, we observed that elevated ESR2 mRNA expression in females with ACC was associated with longer OS and DFS, suggesting the tumor-suppressive role of ERβ." (PMID 39201394, 2024). "On the contrary, the low-risk score group had elevated expressions of tumor suppressing factors, including ESR2." (PMID 36907877, 2023). "To further examine our findings that high ESR2 expression is associated with improved OS, we performed Cox regression multivariable analysis, adjusting for age, tumor size, lymph node status, and grade." (PMID 35304506, 2022). "ESR1 and PGR transcription levels were correlated with the tumor stage (p < 0.05), and the higher expression of ESR1 and ESR2 are associated with higher tumor stage." (PMID 34322374, 2021). "The presence of ESR2 in BC tumor was associated with the levels of proliferation markers such as Ki67, but a high expression of the receptor was shown to improve the overall survival of BC patients treated with tamoxifen." (PMID 32678032, 2020). "Of the 22 upregulated genes, obASCs upregulated estrogen-related genes that have been shown to promote tumor growth, such as ESR2; as well as cell-cycle-related genes associated with proliferation, such as CDKN1C and CDKN2A." (PMID 30897853, 2019). "With this in mind, we suggest the SNP marker rs35036378 (a primary ESR2-deficient pT1 tumor) as a candidate SNP marker of childhood aggressiveness caused by bisphenol A." (PMID 28105927, 2016). "DC-SCRIPT levels were positively associated with tumor grade and ESR1, PGR, and ESR2 steroid hormone receptor expression level and negatively associated with invasive epithelial tumor cell content and tumor size." (PMID 21122099, 2010). "The ESR2 gene encodes ERβ1, a putative tumor suppressor in hormone-dependent malignancies." (PMID 41153361, 2025). "Overall, these findings reveal the dual landscape of ESR2 genetic variation, encompassing both rare driver-like mutations and common functional polymorphisms that could impact hormone-dependent tumor biology." (PMID 41153361, 2025). "Moreover, we observed that low ESR2 expression is associated with longer OS in four tumor types: KIRP, LAML, MESO, and THCA." (PMID 39201394, 2024). "This may suggest that ESR2 is co-expressed within the immune cell compartment, or that ESR2 is expressed in the tumor compartment and is associated to signatures of immune cell infiltration." (PMID 35304506, 2022). "Moreover, we found that the expression of ESR1 and ESR2 were associated with clinical variables such as gender, age, race, grade, stage, and tumor status." (PMID 32536040, 2020). "Clinically, pan-cancer survival analyses indicated worse overall survival (OS) in BRCA for ESR2-Altered cases (HR ≈ 2.25; q < 0.001), but better OS in UCEC (HR ≈ 0.24; q ≈ 0.014) and OV (HR ≈ 0.29; q < 0.001), highlighting a tumor-type-specific association." (PMID 41153361, 2025). "The Wilcoxon rank sum test revealed significantly lower expression levels of CDC42 and ESR2 in tumor samples compared to normal tissues." (PMID 41246859, 2025). "Consequently, the loss of ESR2 in colorectal tissue may promote tumor development." (PMID 41415563, 2025). "Pan-cancer analyses using TCGA further show that high ESR2 mRNA can be favorable in several tumor types yet neutral or adverse in others, reinforcing tissue-, isoform-, and compartment-specific biology." (PMID 41153361, 2025). "β-estradiol (E2) and ESR2 (ERβ) were the strongest activated regulators identified, reinforcing ERβ’s direct role in transcriptional control of key tumor suppressive genes involved in TGFβ signaling, ECM remodeling, metabolic shifts, and cytokine modulation." (PMID 40647431, 2025).
tumor (continued). "Next, we investigated a correlation between tumor grade or stage and ESR2 mRNA expression using the TISIDB database." (PMID 39201394, 2024). "This study presents a comprehensive bioinformatics analysis of the potential role of ESR2 across various TCGA tumor types." (PMID 39201394, 2024). "This intriguing result aligns with existing literature highlighting ESR1 expression in tumour cells and ESR2 expression primarily in normal tissue adjacent to the tumour site." (PMID 38832821, 2024). "The colony formation assay showed that the proliferation of TFAP2A-overexpressing and control tumour cells decreased when ESR2 was knocked down." (PMID 39695171, 2024). "Our analysis displayed that ESR2 mRNA expression was significantly elevated in normal tissue corresponding to eight tumor types, namely, BRCA, COAD, KICH, KIRC, KIRP, and THCA, aligning with the literature." (PMID 39201394, 2024). "Collectively, our results highlight the significant influence of ESR2 mRNA expression on the transcriptomic landscape and the overall metabolism of cancerous cells across various tumor types." (PMID 39201394, 2024). "As a next step, we conducted GSEA of 30 tumor types to elucidate the role of ESR2 in molecular pathways." (PMID 39201394, 2024). "There remains a notable gap in compact and comprehensive analyses of ESR2 mRNA expression levels across diverse tumor types coupled with an exploration of its potential gene network." (PMID 39201394, 2024). "Still, this study constitutes a compact and comprehensive analysis of ESR2 mRNA expression levels across diverse tumor types and an exploration of its potential functional implications." (PMID 39201394, 2024). "In summary, we comprehensively analyzed ESR2 and selected co-expressed gene expression in TCGA tumor types." (PMID 39201394, 2024). "Collectively, our results highlight the significant influence of ESR2 mRNA expression on the transcriptomic landscape and overall metabolism of cancerous cells across various tumor types." (PMID 39201394, 2024). "Even within the same tumor grade, patients with higher ESR2 expression had a worse prognosis for survival." (PMID 38641065, 2024). "The subcutaneous tumours were analysed by IHC, which demonstrated that the expression levels of TFAP2A, ESR2 and Ki67 were decreased in tumours derived from TFAP2A-knockdown cells but increased in tumours derived from TFAP2A-overexpressing cells." (PMID 39695171, 2024). "Out of 24 cancer types for which data were available on TISIDB, only 4 yielded significant results (p-value < 0.05) for the correlation between ESR2 expression and tumor stage." (PMID 39201394, 2024). "The ESR2 (estrogen receptor 2) gene, also known as Erb, ESRB, ODG8, ESTRB, NR3A2, ER-BETA, and ESR-BETA, is usually described as a tumor suppressor." (PMID 36902812, 2023). "Implantation of SW480 cells overexpressing ESR2 to immunodeficient mice issued in lower tumour growth compared to mice implanted with control SW480 cells." (PMID 37831728, 2023). "After transfected with ESR1 or ESR2, both the mRNA and protein expression levels of ESR1 or ESR2 in tumor cells were significantly upregulated." (PMID 36765788, 2023). "Esr2 Y55F loss-of-function mice subjected to ERβ agonist S-equol and PD1 Ab displayed a higher tumor burden compared with wt littermates." (PMID 37686465, 2023). "Protective effects of E2 are, to some extent, lost in CRC tissue as expression of ESR2 is substantially lower in tumours compared to adjacent tissues." (PMID 37831728, 2023). "As during cancer progression, the levels of both ESR2 and miR-34a are modified in tumour tissue, in future it would be of interest to test all studied regulatory relationships in non-cancerous colon cell lines." (PMID 37831728, 2023). "ESR2 can regulate genes in several key pathways, such as tumor suppression, survival, metabolism, and proliferation pathways." (PMID 36902812, 2023).
tumor (continued). "DLBCL appears to be one of the few tumor types in which ESR2 expression is significantly higher in malignant cells compared to their normal counterparts." (PMID 35256592, 2022). "MRPL13, along with other highly altered RBPs, has only been shown to interact with ESR2, a tumor suppressor in breast and other cancer types." (PMID 35453681, 2022). "It is notable that the Esr2 expression in the TME is low in comparison to the ESR2 expression in the tumor cells." (PMID 35804870, 2022). "The activation of ESR2 resulted in reduced MCL tumor growth of MCL tumors that were both sensitive and resistant to a newly developed drug (ibrutinib)." (PMID 35804870, 2022). "ESR1, ESR2, and PGR mRNAs were found to be differentially expressed in different cancer types, and were associated with tumor progression and clinical prognosis." (PMID 34322374, 2021). "In summary, we identified significant differences in the expression levels of ESR1, ESR2, and PGR mRNAs in different cancer types, which associated with tumor progression and clinical prognosis." (PMID 34322374, 2021). "Gene expression in tumor-resistant Esr2 heterozygous females and Esr2 KO females also showed an overall normal WT female gene expression profile for Esr1-dependent genes." (PMID 34068249, 2021). "For analyzing ESR2 expression level versus T cell infiltration in each tumor, the total expression of CD4, CD8α, GZMB (log2 counts per million) was used to assess the infiltration of cytotoxic T-lymphocytes, and correlations were computed vs ESR2 expression." (PMID 33462142, 2021). "The KEGG enrichment result showed that ESR1 and ESR2 significantly correlated genes were mainly enriched in immune response and tumor‐related cellular signaling pathways in most cancer types." (PMID 32536040, 2020). "This trend was also observed when patients were stratified by tumor ESR2 expression, with patients with higher than median ESR2 expression (ESR2 > 3.69) having significantly higher survival rates than patients with lower ESR2 expression after 15 years." (PMID 32144339, 2020). "The pan‐cancer analysis showed significantly different mRNA expression of ESR1 in nine tumor types and ESR2 in four tumor types." (PMID 32536040, 2020). "We got similar results by comparing the mRNA expression of ESR1and ESR2 between exactly matched tumor and normal tissues from the same patients." (PMID 32536040, 2020). "After further adjust the effect of tumor‐related pathological factors, the ESR1 mRNA expression independent associated with survival in LIHC and MESO and ESR2 independent associated with survival in BRCA, KICH, KIRP, LGG, and PAAD." (PMID 32536040, 2020). "We observed that IDO1, IL20RB, PPP3CA, and PLAU were negatively associated with favorable outcomes and were found to participate in tumor progression, whereas ESR2 showed the opposite effect." (PMID 33718118, 2020). "ESR2 showed a low methylation level in eight tumor types, including BLCA, COAC, KIRP, LUAD, LUSC, READ, THCA, and UCEC." (PMID 32536040, 2020). "The ESR2 expression was lower in tumor tissues than healthy tissues in BRCA, COAD, KICH, and PCPG, and higher in CHOL." (PMID 32536040, 2020). "To understand the effect of the ER in different tumor types, we analyzed the correlation of ESR1and ESR2 mRNA level with the molecular subtype of 24 TCGA tumor types." (PMID 32536040, 2020). "Gene expression analysis of the tumours showed that ESR1 likely mediates this effect, as Esr1 was highly expressed in both control and E2-stimulated tumours relative to normal ovary, whereas Esr2 was expressed at much lower levels in MASE-derived tumours." (PMID 29973689, 2018). "Stratification for CDKN2A expression also showed a significantly lower expression of ESR2 in CDKN2Ahigh tumours (p < 0.001)." (PMID 30258198, 2018). "Similar findings were obtained for ESR2 (ERβ) mRNA where increased expression was detected in tumours samples from 24 patients." (PMID 29390981, 2018).
tumor (continued). "Neither was there any significant difference in the expression of ESR2 (ERβ) mRNA in normal mucosal samples from patients who had T1 and T3 tumours (P = 0.53)." (PMID 29390981, 2018). "Methylation levels ≥ 25% were only obtained for the promoters of APC in 44% (8/18), BRCA1 and CDKN2A in 11% (2/18) and ESR2 in 12% (2/17) of the tumor tissues and in addition for ESR2 in 6% (1/18) of the tumor-distant tissues." (PMID 28403857, 2017). "A significant decrease of ESR2 expression levels was observed in polyps and tumours compared to normal mucosa (fresh frozen tissues) or normal tissue from FAP patients (FFPE samples), regardless of heredity." (PMID 29132333, 2017). "In tumor adjacent tissues, the promoter methylation status of ESR2 correlated with that of MGMT (r = 0.704, p = 0.002) and in tumor-distant tissues, the methylation status of APC correlated with that of ABCB1 (r = 0.756, p < 0.001)." (PMID 28403857, 2017). "In case of BRCA1 (r = 0.994, p < 0.001), exon 2 of CDKN2A (r = 0.651, p = 0.003) and ESR2 (r = 0.580, p = 0.015), methylation levels in tumor-adjacent tissues correlated with those in tumor-distant tissues." (PMID 28403857, 2017). "This study revealed higher ESR2 expression in a putative marker function in tumor tissue as compared normal prostate." (PMID 28380417, 2017). "Positive staining for ESR2 (ESR2pos) in tumor cells was detected in 65.1% of tumors and a high staining pattern correlated significantly with a higher SMR3A immunoreactivity score as compared to samples without detectable ESR2 staining (p = 0.044)." (PMID 28166815, 2017). "In contrast to ESR1, ESR2 is usually described as a tumor suppressor in estrogen-sensitive malignancies." (PMID 28166815, 2017). "Apart from breast epithelial tumor cells, ESR2 is also expressed in adjacent infiltrating lymphocytes, fibroblasts, and endothelial cells, all of which are known to influence tumor growth." (PMID 21122099, 2010). "Despite increasing evidence that ERβ1 acts as a tumor suppressor in hormone-dependent cancers, comprehensive investigation of ESR2 nsSNPs—especially within the LBD, DBD, and AF-1/AF-2 domains—remains limited, hindering the clinical application of variant profiling." (PMID 41153361, 2025). "Tumor mutation burden analysis indicated that in 433 STAD samples, 73 samples showed altered mutation frequencies in PRG signatures, with mutation rates of 4% for COL8A1, 3% for DDB1, 3% for PARP1, and 3% for ESR2." (PMID 41004487, 2025). "Previous studies have reported that ESR2 promotes tumour progression by activating MAPK signalling." (PMID 39695171, 2024). "Regarding DFS, ESR2 expression level was considered a prognostic factor in 14 tumor types." (PMID 39201394, 2024). "Furthermore, we analyzed ESR2 mRNA expression in correlation with disease-free survival, yielding significant findings across six tumor types." (PMID 39201394, 2024). "Furthermore, ESR2 mRNA expression was significantly higher in tumor tissue in CHOL, ESCA, HNSC, LIHC, and LUSC, which is consistent with prior research findings." (PMID 39201394, 2024). "Similarly, we found elevated ESR2 expression as a positive prognostic factor in DLBC, aligning with the existing literature associating ERβ activation with tumor growth inhibition." (PMID 39201394, 2024). "Our study found that Remodelin reduces the expression of ESR2, thus it may be able to inhibit the formation of new bone in OS patients, which in turn inhibits tumor growth." (PMID 38347067, 2024). "We analyzed whether ESR2 mRNA expression influenced overall survival and disease-free survival across various TCGA tumor types." (PMID 39201394, 2024). "However, no significant results were obtained in calculations of remaining TCGA tumor types regarding either overall survival or disease-free survival with ESR2 expression level as a prognostic factor." (PMID 39201394, 2024). "Furthermore, we observed a significant correlation between ESR2 expression and tumor grade in two out of eight cancer types." (PMID 39201394, 2024).